PPARA (peroxisome proliferator activated receptor alpha)
Diseases named in the same sentence as PPARA in open-access papers (continued):
Sharing a sentence is not in itself a finding about the gene and the disease.
Alzheimer disease (75 papers, 2008 to 2026). A progressive, neurodegenerative disease characterized by loss of function and death of nerve cells in several areas of the brain leading to loss of cognitive function such as memory and language. "Current evidence suggests that genetic polymorphisms in the PPARα gene, involved in cholesterol and fatty acid (FA) metabolism, are associated with an increased risk of late-onset Alzheimer’s disease (LOAD)." (PMID 38004166, 2023). "A genetic epidemiological study suggested that PPARα single nucleotide polymorphisms (SNPs) were associated with increased Alzheimer's disease risk, although later studies contradicted this finding." (PMID 25705219, 2015). "Since PPARα is also implicated in the pathophysiology of several other neurological disorders (e.g. stroke, Alzheimer’s disease, Parkinson’s disease and epilepsy) besides depression, vortioxetine may possess more beneficial efficacy involving PPARα in the central nervous system." (PMID 34211395, 2021). "As a transcription factor, PPARA-mediated autophagy influences Alzheimer’s disease (AD) pathology, and PPARA agonists can reverse memory deficits and anxiety-like behaviors in experimental mice." (PMID 41465406, 2025). "The neuroprotective effects of PPARα have been confirmed in several disease models, such as stroke, traumatic brain injury, Parkinson’s disease, Alzheimer’s disease and diabetic peripheral neuropathy." (PMID 37111378, 2023). "In actuality, the effect of PPARα on neuroinflammation has been reported in many central nervous system diseases, such as Alzheimer’s Disease and other neurodegenerative disorders." (PMID 36979952, 2023). "Certain studies also indicate that PPARα activation mediates autophagy and reduces cognitive decline in a murine model of Alzheimer disease." (PMID 36979952, 2023). "Their potential for the treatment of Alzheimer’s disease is based on the ability of the plant extract to activate PPAR-α (peroxisome proliferator-activated receptor alpha) and PPAR-γ (peroxisome proliferator-activated receptor gamma) selectively." (PMID 37241796, 2023). "It has also been reported that the PPARα agonist (WY 14.643) was able to protect neurons by regulating mitochondrial fusion and fission in the brain of a transgenic mouse model of Alzheimer’s disease." (PMID 35222033, 2022). "In mammals, PPARα activates autophagy in response to various stresses, including in neurons to clear Aβ in Alzheimer’s disease, and in the liver during inflammation and starvation." (PMID 35285794, 2022). "Recently, it has been demonstrated that PPARα is also involved in the pathogeneses of many neurological disorders such as stroke, Alzheimer’s disease, Parkinson’s disease and epilepsy." (PMID 34211395, 2021). "A recent study conducted using the FAD5X mice model for Alzheimer’s disease also found that ASA binds to peroxisome proliferator-activated receptor alpha (PPARα) and upregulates the expression of brain-derived neurotrophic factor (BDNF) in hippocampal neurons." (PMID 31671812, 2019). "Outcomes of the trial will determine the feasibility of repurposing gemfibrozil as well as other PPARα agonist for Alzheimer’s disease therapy." (PMID 31614690, 2019). "This study identifies statins as ligands of PPARα analyzing the importance of PPARα in the therapeutic success of simvastatin in an animal model of Alzheimer’s disease." (PMID 29949869, 2018). "PPARα has neuroprotective effects in several disease models including stroke, Alzheimer's disease, Parkinson's disease, traumatic brain injury, diabetic peripheral neuropathy, and retinopathy." (PMID 25705219, 2015). "Recent studies showed that agonists of PPARs (PPARα, β, and γ) are protective against brain injury (i.e., ischemic cerebral damage and traumatic brain injury) and neurodegeneration (i.e., Alzheimer's disease and Parkinson's disease)." (PMID 23304113, 2012).
Alzheimer disease (continued). "Specific ligands for PPARα, γ, and δ isoforms have proven effective in the animal models of multiple sclerosis (MS), Alzheimer's disease, Parkinson's disease, and trauma/stroke, suggesting their use in the treatment of neuroinflammatory diseases." (PMID 18670616, 2008). "BEZ, a PPARα agonist, has been used in clinical practice and may be used in the treatment of Alzheimer’s disease, Parkinson’s disease." (PMID 40371339, 2025). "In MAFLD, PPARα shows a protective function with its upregulation of lipid oxidation and mitochondrial biogenesis and transcriptional repression of inflammatory genes, which is similar in Alzheimer’s disease and cardiovascular disease." (PMID 36589809, 2022). "In a mouse model of Alzheimer’s disease, aspirin could inhibit inflammatory gene PPARα expression and attenuate amyloid plaque pathology in brain cells." (PMID 35455688, 2022). "Moreover, the activation of PPARα has anti-inflammatory properties and a beneficial impact on certain neurologic diseases, including Alzheimer’s disease (AD), Multiple sclerosis (MS), Huntington’s disease (HD), and Parkinson’s disease (PD)." (PMID 36359869, 2022). "The most statistically significant transcription factors were STAT3 (Signal Transducer and Activator of Transcription 3) involved in focal adhesion, DNMT1 (DNA Methyl Transferase 1), and PPARA (Peroxisome Proliferator-Activated Receptor Alpha) involved in Alzheimer’s disease." (PMID 34836168, 2021). "PPARα has neuroprotective effects in many disease models including cerebral ischemia/reperfusion, traumatic brain and spinal cord injury, Parkinson's disease, Alzheimer's disease, peripheral neuropathy, ischemic retinopathy, and DR." (PMID 25705219, 2015). "Clinical and basic research findings have suggested that PPARα may have a therapeutic effect in Alzheimer's disease, but these findings remain controversial." (PMID 25705219, 2015). "Caudatin has also displayed neuroprotection in models of Alzheimer’s disease by activating TFEB and the autophagosome-lysosomal pathway mechanism of action, while also modulating PPARα." (PMID 40959450, 2025). "Neuroprotective effects of PEA are mediated by peroxisome proliferator-activated receptor-alpha (PPAR-α) activation according to experimental evidence regarding PD, Alzheimer’s disease, traumatic brain injury and several neuropsychiatric disorders." (PMID 36090655, 2022). "An interesting study aimed at correlating PPARα activation and the expression of brain-derived neurotrophic factor (BDNF) in hippocampal neurons demonstrated an improved learning and memory in an animal model of Alzheimer disease via PPARα." (PMID 27013951, 2016).
Hyperglycemia (73 papers, 2008 to 2026). An increased concentration of glucose in the blood. "It has been proved that expression of PPARα was reduced by hyperglycemia, and SIRT1 activated PPARα pathway to reduce ROS in diabetic vascular diseases." (PMID 33304318, 2020). "Furthermore, upregulated hepatic ketogenesis and concurrent upregulation of renal gluconeogenic gene expression are associated with fasting hyperglycemia in DIO mice, an effect that is blunted in PPARα−/− mice." (PMID 38604598, 2024). "We hypothesized that PPARα activation would prevent this hyperglycemia-induced increase in epithelial permeability." (PMID 38110453, 2023). "In detail, treating diabetic mice with SGLT2i attenuated hyperglycaemia, dyslipidaemia, renal lipotoxicity, glomerular damage, and albuminuria, as well as increased renal PPARα and PPARγ with concurrent decreases in several inflammatory and oxidative stress markers." (PMID 38139208, 2023). "Although PPARα activation by Pema did not affect hyperglycemia, glycolytic genes, or G6pc expression, which is associated with ChREBP activation by fructose, Tofo tended to reduce the expression levels of these genes." (PMID 35203369, 2022). "Similarly, PPARα KO mice develop marked age-dependent hyperglycemia, and after 24-h fasting, severe hypoglycemia accompanied by elevated plasma insulin concentrations." (PMID 32708786, 2020). "In addition, hyperglycemia blocks FFA oxidation at the level of gene expression via inhibiting PPARα (peroxisome proliferator-activated receptor alpha) that regulates the expression of enzymes necessary for mitochondrial β-oxidation." (PMID 30248910, 2018). "Moreover, experiments with Apo-E deficient mice proved that fenofibrate could also act in a lipid/glucose metabolism independent manner, since the infarct size was still reduced by the PPARα agonist after these mice developed hyperglycemia." (PMID 28603485, 2017). "Literature has shown that PPARα activity is compromised under hyperglycemia conditions, and SIRT1 can enhance antioxidant capacity by activating PPARα activity and improve diabetic cardiovascular complications." (PMID 35739982, 2022). "Meanwhile, hyperglycemia-induced phosphorylation of hepatic ERK1/2 and PPARα was significantly attenuated in db/db mice treated with zopolrestat or AR shRNA." (PMID 22110479, 2012). "In addition, HFD-fed mice showed fasting hyperglycemia along with upregulated renal gluconeogenic gene expression, which was blunted in HFD-fed PPARα−/− mice." (PMID 38604598, 2024). "We sought to determine if hyperglycemia directly increases intestinal epithelial permeability, and if any glucose-induced effects may be prevented pharmacologically with the FDA-approved PPARα agonist, fenofibrate." (PMID 38110453, 2023). "In our study, the subchronic treatment with fenofibrate and metformin, at low doses, lowers the hyperglycemia but does not improve the glucose tolerance in DB-rats compared with CT-rats, an effect most probably mediated by PPARα." (PMID 27069466, 2016).
non-alcoholic steatohepatitis (72 papers, 2010 to 2026). "High affinity is revealed between FABP1 and PPARa, indicating their functional interactions, which is linked to the progression of fatty liver and nonalcoholic steatohepatitis." (PMID 38464590, 2024). "A recent landmark phase 2b clinical trial demonstrated the clinical benefit of pan-PPARα/γ/δ agonist lanifibranor in non-alcoholic steatohepatitis to slow the progression of fibrosis (NCT03008070)." (PMID 37686465, 2023). "Nevertheless, the increased expression level of the Pparα–Fabp1 axis was always found in DIO mice, and the suppression of the Pparα–Fabp1 axis was considered as a treatment for nonalcoholic steatohepatitis, suggesting the potential threat of a high-BCAA diet." (PMID 36982473, 2023). "The main results of our study demonstrate that liver CB1 mRNA expression is induced in nonalcoholic steatohepatitis and correlates negatively with hepatic PPARα expression, which suggests a deleterious role of CB1 in NAFLD." (PMID 24864249, 2014). "Furthermore, PPARα-agonists can increase the stability of atherosclerotic plaques, reduce the risk of atherothrombosis, slow the progression of intimal hyperplasia following surgery, and reduce hepatic fat accumulation leading to non-alcoholic steatohepatitis/fatty liver disease (NASH/NAFLD)." (PMID 23721199, 2013). "As such, PPARα/β/γGPR40 pan-agonist RLA8A was designed to ameliorate non-alcoholic steatohepatitis and fibrosis in mice, leaving the answer open if this quadruple targeting may also counteract cancer development." (PMID 37686465, 2023). "PPARα and PPARγ agonists have the potential to correct non-alcoholic steatohepatitis damages." (PMID 34593018, 2021). "In addition, pirfenidone prevented myocardial steatosis and fibrosis in a mouse model of nonalcoholic steatohepatitis (NASH) by overexpressing PPARα, PPARγ, ACOX1, and CPT1A protein levels and decreasing Timp1, Col I, Col III mRNA levels." (PMID 33809061, 2021). "CGA alleviates liver inflammation during non-alcoholic steatohepatitis (NASH) progression by blocking the LPS-TLR4-MyD88 signaling pathway via direct binding to MyD88 and by activation of Nrf2/PPARα signaling." (PMID 38612964, 2024). "In this study, we evaluated that CS improves non-alcoholic steatohepatitis through down-regulating SREBP-1c and a PPARα-independent pathway in high-fat diet-fed rats." (PMID 36192786, 2022). "FF, the fibrates class of lipid-lowering drugs, is commonly used in the treatment of HLD as a PPARα agonist for reducing cardiovascular risks and treating NAFLD/nonalcoholic steatohepatitis, as well as improving the GLU tolerance and lowering adiposity." (PMID 24876871, 2014). "Because bilirubin protects the liver by reducing the incidence of nonalcoholic steatohepatitis, which another study showed may progress to cirrhosis and HCC, bilirubin may inhibit cancer by binding to PPARα." (PMID 40291905, 2025).
Hypertension (71 papers, 2008 to 2025). The presence of chronic increased pressure in the systemic arterial system. "In summary, we showed that a PPARα deficiency in VSMCs significantly exacerbated the hypertension, vascular remodeling, stiffness, and oxidative stress." (PMID 36552585, 2022). "A PPARα deficiency in the VSMC significantly aggravated the Ang II-induced hypertension and vascular stiffness, with little influence on the cardiac function." (PMID 36552585, 2022). "A PPARα deficiency in VSMCs significantly exacerbates vascular remodeling upon an Ang II stimulation, leading to an increased stiffness and hypertension." (PMID 36552585, 2022). "In many clinical studies, PPARα has also been linked to the start of cardiovascular disease, atherosclerotic alterations, and hypertension in numerous clinical trials." (PMID 35886059, 2022). "Although we observed that a PPARα activation by Wy14643 attenuated vascular remodeling and hypertension in a PPARα deficiency, it is noteworthy that Wy14643 only partially through VSMC-PPARα improves hypertensive vascular remodeling." (PMID 36552585, 2022). "In PPARα-deficient THM animals this hypertension is totally abolished, and this is accompanied by a reduction in plasma renin and by a normalization of serum aldosterone." (PMID 20613959, 2010). "PPARα is implicated in vascular damage, cardiac disease, hypertension, and lipid disorders." (PMID 35886059, 2022). "Cyp4a8 is also a target of PPARα (peroxisome proliferator activated receptor alpha) signaling and its expression has been suggested to explain sex and strain differences in the susceptibility to hypertension and target organ damage." (PMID 21118493, 2010). "For instance, offspring of pregnant dams fed a protein-restricted diet had decreased methylation status of their hepatic PPARα and GR genes, which in turn may be the underlying mechanism of impaired fat and carbohydrate metabolism and later hypertension induced by maternal protein restriction." (PMID 28025503, 2016). "Another study offered similar evidence by showing that a combination of low doses of PPARα (fenofibrate) and PPARγ (rosiglitazone) activators reduced the hypertension development in the model of Ang II–infused Sprague–Dawley rats." (PMID 40137963, 2025). "The differences in PPARα activity driven by sex hormones contrast with the PPARγ activity that appears to have a similar effect on hypertension in both sexes in mice." (PMID 40829644, 2025). "The knockdown of VSMC PPARα significantly aggravated the Ang II-induced hypertension and vascular stiffness." (PMID 36552585, 2022). "Taken together, these data suggest that PPARα plays a critical protective role in Ang II-induced hypertension via attenuating ROS production in VSMCs, thus providing a potential therapeutic target for hypertensive diseases." (PMID 36552585, 2022). "Agonist activation of PPARα has been shown to protect against acute myocardial ischemia, myocardial remodeling and hypertension, hypertrophy, diabetic cardiomyopathy, atherogenesis and vascular injury." (PMID 34944662, 2021). "Previous study showed that resveratrol increased the levels of sirtuin-1 (SIRT1) and PPARα to mediate its protective effect on hypertension under maternal HFD in the kidneys of male progeny." (PMID 33519432, 2020). "The increases in blood pressure and endothelial dysfunction observed upon Ang II-induced hypertension are improved by activation of PPARα, which modulates NOX activity in vascular cells." (PMID 30620754, 2019). "For example, angiotensin-infused Pparα−/− mice displayed elevated mean arterial pressure compared to WT, and activation of PPARα attenuated Ang II-induced hypertension in WT mice." (PMID 26649033, 2015). "The early significant reduced expression of the antioxidant AMPK/PPARα/UCP2 pathway that progressed throughout lifetime may contribute to explain higher predisposition of SHRSP to oxidative stress dependent target organ damage in the context of severe hypertension." (PMID 26023797, 2015).
Hypertension (continued). "A recent study documented that increased PPARα expression can also play a protective role in hypertensive renal injury in rats with hypertension induced by NO withdrawal and high salt diet." (PMID 20613959, 2010). "In addition, other evidence about PPAR isoforms is that activation of PPARα prevents or attenuates hypertension." (PMID 40137963, 2025). "Overall, PPARα agonists have hypolipidemic, vascular, and anti-inflammatory actions that could contribute to blood pressure lowering in hypertension." (PMID 37427406, 2023). "Moreover, the PPARα agonist Wy14643 exhibits anti-remodeling and anti-hypertension effects in a VSMC PPARα-dependent manner." (PMID 36552585, 2022). "When considering that the function of PPARs is recognized to be important for the development of hypertension, activation of PPARα by URB597 administration in DOCA-salt rats may represent one of the protective mechanisms against the progression of hypertension." (PMID 30223427, 2018). "Furthermore, the parallel eNOS down-regulation observed exclusively in SHRSP over lifetime, consistent with reduced PPARα expression, may also contribute, through decreased nitric oxide production, to promote both hypertension and vascular damage in SHRSP." (PMID 26023797, 2015). "The existence of antihypertensive and antiatherogenic actions of PPARα are also challenged by work with the Tsukuba hypertensive mouse (THM), a model of Ang II-induced hypertension." (PMID 20613959, 2010). "In this review we summarize current knowledge about the role of PPARγ and PPARα in the functioning of the RAAS and discuss the possible modulation of RAAS­dependent hypertension by these transcription factors at the level of gene expression." (PMID 20613959, 2010). "Gene expression of RAAS molecules is modulated by PPARγ, and to a lesser extent by PPARα, making the ligands of these transcription factors potential blood pressure modulating drugs in RAAS-dependent hypertension." (PMID 20613959, 2010). "Transcription of angiotensinogen seems also to be regulated by PPARα, although the value of PPARα as a therapeutic target in RAAS dependent hypertension should be evaluated." (PMID 20613959, 2010). "Evidence from clinical studies and animal hypertension models have demonstrated that PPARα, PPARγ, and FXR agonism can lower blood pressure and decrease end organ damage which could be useful for the treatment of hypertension in patients with metabolic diseases." (PMID 37427406, 2023). "However, the role of PPARα in the regulation of the RAAS is disputed, and unwanted hepatotoxic and cardiac effects of currently available PPARγ ligands limit the use of these drugs in hypertension management." (PMID 20613959, 2010). "Thus these data, while confirming that PPARα regulates the RAAS, indicate that PPARα activation in this model aggravates hypertension and fails to protect against atherogenesis." (PMID 20613959, 2010).